ACE (angiotensin I converting enzyme)
Diseases named in the same sentence as ACE in open-access papers (continued):
Sharing a sentence is not in itself a finding about the gene and the disease.
cancer (continued). "Although Ang-II has been reported to regulate growth, adhesion, invasion and cell migration in certain cancer cells, this is the first report of Ang-II-induced melanocytes proliferation and migration mediated by binding to ACE." (PMID 27992423, 2016). "There is also some preliminary evidence that ACE inhibitors have the potential to ameliorate cancer cachexia, at least in NSCLC patients." (PMID 26856534, 2016). "A large number of these biofunctional peptides have been isolated from food proteins including anti-cancer, anti-inflammatory, immunomodulatory, muscle-stimulating and angiotensin converting enzyme (ACE) inhibitory peptides." (PMID 26076110, 2015). "The expression of ACE is upregulated in several cancers with functions of angiogenesis and tumor cell growth." (PMID 25889770, 2015). "This can include administration of cardiac treatment such as beta-blockers, ACE inhibitors, and dexrazoxane; selection of alternative cancer regimens or dose adjustment; and transient cessation of cancer treatment." (PMID 26339242, 2015). "An antiangiogenic effect of ACE inhibitors has been observed in various cancer models, where ACE inhibitors have been shown to attenuate tumor growth and VEGF levels." (PMID 25401104, 2014). "Although more convenient once-a-day ACE inhibitors have since come on the market, we chose to use captopril because so much of the empirical anti-cancer data was collected specifically on captopril." (PMID 25211298, 2014). "Blockade of the classical RAS through AT1R blockade or ACE inhibition reduces tumour growth in several experimental mouse models of cancer." (PMID 21703011, 2011). "Considering the extensive role of ACE in the pathogenesis of cancers, a meta-analysis was performed on all eligible case-control studies to estimate the association between this polymorphism and cancer risks." (PMID 22151803, 2011). "Several protease targeted drugs are routinely used in the clinic, for example, ACE inhibitors, and others are in pre-clinical development, including neutralizing antibodies against both cathepsin B and uPA for cancer treatment." (PMID 22093547, 2011). "RAS expression has been described in various cancer cells and tissues and there is strong evidence that ACE inhibition can inhibit tumor growth." (PMID 20380732, 2010). "It has been reported that oyster extracts have many bioactive peptides, such as ACE (angiotensin-converting enzyme) inhibitory peptides, anti-fungal peptides and anti-cancer peptides." (PMID 20390104, 2010). "This increase in ACE expression would need to be taken into consideration if targeting ACE in anti-cancer therapies." (PMID 20380732, 2010). "In addition, Ang II receptor antagonists and angiotensin I-converting enzyme inhibitors currently used for human clinical hypertension treatment attenuate growth of human cancer cells in experimental animals and may reduce the risk of several human cancers." (PMID 20181281, 2010). "Epidemiological studies suggest that the incidence of cancer and cancer deaths are lower in hypertensive patients taking ACE inhibitors than in those treated with other classes of antihypertensives." (PMID 15162145, 2004). "We constructed a pan-cancer expression profile for the ACE and HSPB8 genes." (PMID 41490177, 2026). "ACE inhibitors may aid in cancer prevention by lowering angiotensin II levels, which are associated with tumor growth and angiogenesis." (PMID 39857949, 2025). "Thus, while our study highlights ACE as a potential biomarker for anti-PD-1 patient selection, the functional role of ACE in cancer and cancer immunology warrants further investigation." (PMID 40235590, 2025). "While most of these studies conclude that overexpression of the ACE is related to poor prognosis of cancer, others indicate that the ACE may have anti-cancer effects." (PMID 40710006, 2025). "Cancer, inflammatory biomarkers, and angiotensin-converting enzyme (ACE) levels were normal." (PMID 40978889, 2025).
cancer (continued). "Furthermore, cancer-associated fibroblasts (CAFs) and tumor-infiltrating immune cells such as myeloid-derived suppressor cells (MDSCs) express the AT1 receptor and ACE." (PMID 38338778, 2024). "The success of the ACE-overexpressing murine macrophage model, ACE 10/10, in treating microbial infections and cancer opens a new avenue into whether ACE overexpression in human macrophages shares these benefits." (PMID 39000163, 2024). "Therefore, in line with these previous results, our results support a chemopreventive effect of ACE inhibition mediated by ACE gene expression and downregulating cancer FE genes." (PMID 39518949, 2024). "Pacific oyster (Crassostrea gigas) has shown promise experimentally exhibiting various bioactivities including antimicrobial, antioxidant, anti-inflammatory, angiotensin-converting enzyme (ACE)-inhibitory, anti-cancer, and promotion of sexual reproductive hormones." (PMID 36677709, 2023). "Cancer development may be influenced by the balance between the ACE/Ang II/AT1R and the ACE2/Ang 1–7/Mas receptor pathways." (PMID 37891636, 2023). "In addition, FFVAPFPEVFGK was suggested to have not only ACE inhibition and anti-cancer activity but also reducing and/or antioxidant and NO2−-reducing activity." (PMID 38201040, 2023). "Beta blockers and Angiotensin converting enzyme (ACE)-inhibitors have been shown in several studies to improve left ventricular ejection fraction (LVEF) in patients with already established LVEF decline following cancer therapy." (PMID 36158986, 2022). "The observed restriction of an association of genetically proxied ACE inhibition with risk of colon, but not rectal, cancer is consistent with evidence that mRNA and protein levels of ACE are enriched in the colon but not in rectal tissue." (PMID 35113855, 2022). "There was a single trial with cumulative exposure >3 years, where there was ACE-inhibitor treatment in both study arms (i.e. ONTARGET trial, new cancer occurrence 8.4% with ARB+ACE-inhibitor vs. 7.5% ACE-inhibitor only, RR 1.11 [95% CI 1.00 to 1.23], p = 0.05)." (PMID 35235571, 2022). "Although the exact mechanism for the protective effect of RAAS inhibitor against cancer is not fully known, ACE inhibitors reduce the conversion of angiotensin I to angiotensin II, and ARBs selectively inhibit the unfavorable actions of AT1R by maintaining the protective function of AT2R signaling." (PMID 35477724, 2022). "There was no increase in risk of cancer with ARB+ACE-inhibitor compared to ACE-inhibitor only in trials with cumulative exposure ≤ 3 years)." (PMID 35235571, 2022). "Supermeres harbor multiple cargos that are related to a large panel of pathologies, including Alzheimer’s (e.g., amyloid precursor protein, APP) and cardiovascular (e.g., angiotensin-converting enzyme, ACE) diseases as well as cancer (e.g., MET proto-oncogene and receptor tyrosine kinase)." (PMID 36291183, 2022). "The role of ACE in the tumour microenvironment and cancer has been the subject of intense research." (PMID 36016727, 2022). "NOS3, ACE, and INSR have high mutation frequencies in most cancer types." (PMID 35513851, 2022). "Altered expression of ACE or ACE2 is associated with initiation and progression of many cancers." (PMID 36335375, 2022). "Besides, ACEI, stopping the transition of Ang I to Ang II catalyzed by ACE, still has a controversial impact on incidence and mortality of cancer." (PMID 34221978, 2021). "Additionally, clinical trials of patients receiving thoracic irradiation for cancer treatment have demonstrated benefits for the use of ACE inhibitors." (PMID 33616187, 2021). "In addition, ACE inhibitors including lisinopril, reduced the prevalence of radiation-induced pneumonitis in cancer patients treated with radiotherapy, indicating efficacy in humans." (PMID 34079456, 2021).
cancer (continued). "Ayyash demonstrated that camel milk fermented with probiotic bacteria from camel milk had the greater anti-cancer potential by inhibiting angiotensin-converting-enzyme (ACE), α-amylase and α-glucosidase, as well as antidiabetic and antihypertensive potential compared to bovine fermented milk." (PMID 34067516, 2021). "ACE inhibitors have been studied as potential cancer treatments." (PMID 34399734, 2021). "Other cardioprotective agents, including beta-blockers (BB), angiotensin-converting enzyme (ACE) inhibitors, and angiotensin receptor blockers (ARBs), have demonstrated effectiveness in reducing the risk of cardiotoxicity among cancer patients, as evidenced by various RCTs." (PMID 34406595, 2021). "In contrast, a retrospective clinical study found that ACE inhibitors or ARBs and higher RT doses were related to lower overall survival after the diagnosis of cancer in those patients who were treated with thoracic RT and later underwent percutaneous coronary interventions." (PMID 34884782, 2021). "ACEIs/ARBs (ACE/ANG II/AGTR1 axis inhibitors) might benefit cancer patients with SARS-CoV-2 infection." (PMID 34671200, 2021). "Interestingly, patients treated with ACE inhibitors have a lower than expected chance of developing cancer." (PMID 33858332, 2021). "Additionally, the positive effects of an early initiated therapy with ACE inhibitors and beta-blockers are discussed in the context of other cancer therapies to help prevent heart failure from cancer therapy in general." (PMID 32266294, 2020). "ACE inhibitors including enalapril also have been confirmed to suppress tumorigenesis and angiogenesis in other cancer mouse models, and that suppression of the VEGF level may be involved in the mechanism of this inhibitory effect." (PMID 32581212, 2020). "Some evidence indicated that using Angiotensin receptor blockers (ARBs) or angiotensin-I-converting enzyme inhibitors may even protect against cancer." (PMID 31174518, 2019). "Several findings have shown that the ACE inhibitors may possibly reduce the incidence of cancer and may protect against it." (PMID 31312309, 2019). "According to the data from basic science, ACE inhibitors or ARB might have a protective role in cancer." (PMID 29514670, 2018). "In a subsequent study with the same cancer model, these investigators demonstrated a distinct cancer cell-associated RAS expression with increased expression of AT1R, and again, ACE inhibitor treatment led to a reduced tumor volume and decrease in AT1R expression." (PMID 30103733, 2018). "However, they did observe an increase in cancer risk in patients taking both an ARB and an ACE inhibitor." (PMID 28791183, 2017). "Furthermore, researchers have suggested that the ACE-Ang II-AT1R pathway is related to the biology process leading to cancer." (PMID 28533754, 2017). "Additionally, in several animal models of cancer, both angiotensin-converting enzyme (ACE) inhibitors and AT1 angiotensin receptor subtype blockers (ARBs) inhibit tumor growth." (PMID 28791183, 2017). "There are several clinical evidences showing the chemopreventive effects of ACE-blocking in cancer." (PMID 27992423, 2016). "ACE inhibitors (ACEi) have been assessed in cancer to characterize angiotensin functions in tumor growth, angiogenesis, and metastasis, and were shown to inhibit cell proliferation and tumor progression in several cancer models." (PMID 25741281, 2015). "Previous work by Yeh and colleagues reported that cardiac medications, such as ACE inhibitors and beta blockers, may be effective in patients being treated for cancer." (PMID 26300916, 2015). "The appropriate length of treatment with cardiac medications such as beta-blockers and ACE inhibitors in patients experiencing cardiotoxicity during cancer therapy is unknown." (PMID 26339242, 2015). "Given the important roles of ACE in cancer etiology, it is possible that genetic variations of the ACE gene may modulate the risk of cancer." (PMID 22151803, 2011).
cancer (continued). "Further screening of these articles, three of them were excluded for being not relevant to cancer risk with ACE gene polymorphism." (PMID 22151803, 2011). "Experimentally, ACE-Is and AT1RAs decrease angiogenesis and cellular proliferation and favor cellular differentiation, which could explain the protection of ACE-Is against cancer." (PMID 21085521, 2010). "Furthermore, the anti-angiogenic effect of ACE inhibitors has been shown in various experimental animal models of cancer." (PMID 20431722, 2010). "Some epidemiological evidence also suggests protective effects of ACE inhibitors on cancer." (PMID 19061507, 2008). "The idea that ACE inhibitors might play a protective role in cancer was suggested by observations of reduced incidence of breast and lung cancer in patients undergoing long-term treatment with the captopril, lisinopril, or enalapril." (PMID 18947424, 2008). "Here we present additional evidence of a potential negative association between cancer and the use of ACE inhibitors in a diabetic population." (PMID 19061507, 2008). "Cancer and PUD were significantly associated with ACE inhibitors therapy." (PMID 19061507, 2008). "Finally, the quantification of ACE mRNA showed that expression was present in carcinoma, although again in lower amounts than in normal tissue." (PMID 16755291, 2006). "Medications like calcium channel blockers, beta-blockers, and angiotensin-converting enzyme (ACE) inhibitors, trimetazidine, statins, N-acetylcysteine (NAC), and dexrazoxane have demonstrated promise in lowering both the frequency and intensity of cardiotoxic effects linked to cancer therapies." (PMID 40863337, 2025). "Interestingly, several lines of study appear to support our notion that ACE inhibitors may improve the overall prognosis of cancer patients taking sunitinib." (PMID 39895626, 2025). "Furthermore, inhibition of the N-terminal ACE-active site may have important clinical applications in facilitating hematopoietic recovery after aggressive cancer chemotherapy by controlling the hematopoietic cycle and stem cell proliferation." (PMID 39065005, 2024). "Of note, ACE expression in macrophages was confirmed at the RNA and protein levels in THP1-derived macrophages, with the highest expression in M2 macrophages harboring an immunosuppressive phenotype and associated with cancer development, supporting an involvement of ACE pathways in carcinogenesis." (PMID 35801591, 2022). "Likewise, there was little evidence of association of genetically proxied ACE inhibition with these cancers in histological subtype-stratified analyses." (PMID 35113855, 2022). "This review seeks to highlight the need for further research covering ACE inhibitor therapeutics and their potential role in improving autoimmune conditions, cancer, or how they may contribute to immunocompromise during infection and neurodegenerative diseases." (PMID 36016727, 2022). "Moreover, there is a statistically significant increase in the risk of cancer with ARBs even in patients without background ACE-inhibitor treatment, as long as there is enough exposure." (PMID 35235571, 2022). "Our results suggest that the ACE I/D polymorphism does not affect cancer risk." (PMID 33579229, 2021). "While data from the SOLVD and CHARM trials seem to show a positive correlation between ACE inhibitors or angiotensin receptor blockers (ARBs) and risk of cancer development, in a large meta-analysis, RAAS blockers showed a favorable effect on all cancer endpoints [39•]." (PMID 34181210, 2021). "Despite the differences between the studies included in the analysis, the results of our study suggest that the ACE I/D polymorphism may not lead to cancer risk, which is consistent with the findings of Cheng and Wang." (PMID 33579229, 2021).
cancer (continued). "However, for Angiotensin Converting Enzyme (ACE)-Inhibitory, whether it has an anti-tumor effect is still unclear, some recent studies had demonstrated that Angiotensin Converting Enzyme (ACE) Inhibitory could induce apoptosis of cancer cell." (PMID 32788609, 2020). "Notably, the reduced risk for cancer progression in patients submitted to ACE inhibitors or AT1 receptor blockers has not been seen with other antihypertensive medications, suggesting the existence of an adjuvant effect for angiotensin blockers." (PMID 32503281, 2020). "Recent analysis suggested that the ACE I/D polymorphism might not be a common risk factor for overall cancer susceptibility." (PMID 25889770, 2015). "Despite of these differences, our study also indicated the ACE I/D polymorphism might not contribute to the risk of cancer, which is consistent with Ruiter's study." (PMID 22151803, 2011). "In summary, this meta-analysis suggests that the I/D polymorphism in the ACE gene may not contribute to susceptibility to cancer." (PMID 22151803, 2011). "Although the exact mechanism of this enzyme in cancer etiology is not so clear, our results may indicate that ACE I/D polymorphism may not influence cancer risk." (PMID 22151803, 2011). "This meta-analysis suggested that the ACE D/I polymorphism might not contribute to the risk of cancer." (PMID 22151803, 2011). "ACE inhibitors retard growth of cancer cells in vitro and inhibit tumour growth in vivo, possibly through an effect on angiogenesis, while long-term use of ACE inhibitors may protect against the development of cancer." (PMID 16052213, 2005). "Five listed peptides are Angiotensin-I-converting enzyme (ACE-1; EC3.4.15.1) inhibitory peptides derived from a red alga, while two from Chlorella vulgaris have anti-cancer and antioxidative bioactivities." (PMID 39997177, 2025). "The study found that patients treated with Angiotensin Converting Enzyme (ACE) inhibitors, beta blockers, and thiazide diuretics had decreased cancer-specific mortality." (PMID 40093321, 2025). "Our findings provide actionable targets (CACNA1C, CALM1, ACE, and LTA4H) for drug repurposing trials and underscore the clinical importance of personalized antihypertensive therapy in cancer prevention." (PMID 40535814, 2025). "Clinical evidence indicates that RAS inhibitors (RASi), such as ACE inhibitors, can impede tumor progression, further highlighting the detrimental role of RAS in cancer." (PMID 41301459, 2025). "Antioxidant, anti-inflammatory (LOX, COX-2 inhibition), antihypertensive (ACE inhibition), and antiproliferative effects on AGS and HT-29 cancer cells were evaluated." (PMID 39683849, 2024). "In cancer patients treated with TZ, 21.9% developed HF; regular LVEF assessments and antihypertensive medications like ARBs and ACE inhibitors are crucial for managing cardiotoxicity and improving outcomes." (PMID 39238728, 2024). "Since some cancers express renin, ACE, and Ang II receptors, there is the potential involvement of the local renin-angiotensin system in growth-promoting events, therefore raising the prospect that Ang II may be involved in the development of cancer, as suggested by Sun." (PMID 37627246, 2023). "The human MMPs are major targets of small inhibitors with ncAAs, due to their roles in cancer, also the ADAM, ACE and TACE proteases are still interesting targets (Section 3.5)." (PMID 37762340, 2023). "Similarly, there was evidence of a significant relationship between cumulative-exposure to ARBs and risk of cancer in patients not receiving ACE-inhibitor treatment in either of the study arms (slope = 0.09 [95% CI 0.03 to 0.16], z = 2.73, p = 0.006 with the fixed effect regression method)." (PMID 35235571, 2022). "Detrimental effects of the classical arm of the RAS, including ACE, AngII, and the AngII receptor type 1 (AT1), in cancer progression, angiogenesis and metastasis have been extensively documented, and their expression in the oral cavity has been demonstrated." (PMID 35409002, 2022).